PDE3B (phosphodiesterase 3B)
Description:
Cyclic nucleotide phosphodiesterase with a dual-specificity for the second messengers cAMP and cGMP, which are key regulators of many important physiological process. Regulates angiogenesis by inhibiting the cAMP-dependent guanine nucleotide exchange factor RAPGEF3 and downstream phosphatidylinositol 3-kinase gamma-mediated signaling. Controls cardiac contractility by reducing cAMP concentration in cardiocytes (By similarity).
Synonyms: HcGIP1; cGIPDE1
Tractability: Small molecule: an approved drug acts on it; a structure with a bound ligand is known; a high-quality ligand is known; it has a high-quality binding pocket; it belongs to a druggable protein family. Antibody: UniProt predicts a signal peptide or a membrane-spanning region. PROTAC: ubiquitination databases record sites on it; a small molecule that binds it is known.
Target class: Phosphodiesterase; Enzyme; Phosphodiesterase 3B; Phosphodiesterase 3
Safety:
Unwanted effects reported when the protein is acted on. In parentheses: how it was acted on, where the effect was seen, and who reports it.
hypotension (inhibition; cardiovascular system; source: Urban et al. (2012))
increased mortality in heart failure patients (inhibition, chronic dosing; cardiovascular system; source: Urban et al. (2012))
tachycardia (inhibition; cardiovascular system; source: Urban et al. (2012))
thrombocytopenia (inhibition, chronic dosing; cardiovascular system; source: Urban et al. (2012))
ventricular arrhythmias (inhibition; cardiovascular system; source: Urban et al. (2012))
Gene: Protein-coding gene on chromosome 11 (14,643,663 to 14,874,614, forward strand). Ensembl gene ENSG00000152270.
Subcellular location: Membrane
Subcellular location (Human Protein Atlas): Endoplasmic reticulum
Pathways (Reactome):
Signal Transduction: G alpha (s) signalling events; PDE3B signalling
Gene Ontology:
Molecular function: 3',5'-cyclic-AMP phosphodiesterase activity; 3',5'-cyclic-nucleotide phosphodiesterase activity; protein binding; 3',5'-cyclic-GMP phosphodiesterase activity; protein kinase B binding; phosphoric diester hydrolase activity
Biological process: negative regulation of angiogenesis; negative regulation of cell adhesion; negative regulation of lipid catabolic process; G protein-coupled receptor signaling pathway; insulin receptor signaling pathway; negative regulation of adenylate cyclase-activating G protein-coupled receptor signaling pathway; negative regulation of cAMP/PKA signal transduction; negative regulation of cell adhesion mediated by integrin; signal transduction
Cellular component: guanyl-nucleotide exchange factor complex; membrane; cytosol; endoplasmic reticulum; Golgi apparatus
Genetic constraint (gnomAD): Loss-of-function variants: 34 observed, 47.39 expected, observed/expected ratio (o/e) 0.72, 90% interval 0.55 to 0.95. The synonymous counts are far from expectation, so gnomAD's model fits this gene poorly and the ratio says little. Missense variants: 957 observed, 874.68 expected, observed/expected ratio (o/e) 1.09, 90% interval 1.04 to 1.15. Synonymous variants: 457 observed, 362.32 expected, observed/expected ratio (o/e) 1.26, 90% interval 1.17 to 1.36.
Homologues: Orthologues: chimpanzee PDE3B (99% identical), macaque PDE3B (97% identical), rabbit PDE3B (87% identical), pig PDE3B (86% identical), mouse Pde3b (81% identical), dog PDE3B (79% identical), rat Pde3b (78% identical), guinea pig PDE3B (69% identical), zebrafish pde3b (62% identical), tropical clawed frog pde3b (60% identical), dog PDE3B (52% identical), Caenorhabditis elegans pde-3 (22% identical), and 3 more. Paralogues in human: PDE3A (43% identical), PDE1C (15% identical), PDE4A (14% identical), PDE1B (14% identical), PDE1A (14% identical), PDE4D (14% identical), PDE8B (13% identical), PDE4B (13% identical), PDE8A (13% identical), PDE4C (13% identical), PDE6C (12% identical), PDE2A (12% identical), and 8 more.
Diseases named in the same sentence as PDE3B in open-access papers:
PDE3B is named in the same sentence as 62 diseases in open-access papers, as found by Europe PMC text mining. Sharing a sentence is not in itself a finding about the gene and the disease. The quoted sentences say what the papers report.
Obesity (19 papers, 2007 to 2025). Accumulation of substantial excess body fat. "Interestingly, the core variable species L. lactis was positively correlated with those genes such as AdipoQ, Irs1, Cd 36, and Pde3b involved in obesity associated pathways." (PMID 31708891, 2019). "As with PDE3B, this may also be due to increased inflammatory signaling associated with obesity as the PDE10A promotor harbors a binding site for the pro‐inflammatory transcription factor NF‐kappaB in mice and humans." (PMID 27247380, 2016). "Results reported here suggest that PDE3B and/or its downstream signaling partners might be important regulators of energy metabolism in adipose tissue, and potential therapeutic targets for treating obesity, diabetes and their associated metabolic disorders." (PMID 28084425, 2017). "Results reported here suggest that PDE3B and/or its downstream signaling partners might be important regulators of energy metabolism and inflammation in adipose tissue, and potential therapeutic targets for treating obesity, diabetes and their associated metabolic disorders." (PMID 28084425, 2017). "Both TBK1 and IKKε are induced in response to obesity-dependent inflammation, and appear to phosphorylate PDE3B on the same residues with equal efficiency." (PMID 24368730, 2013). "Among genes that may regulate basal lipolysis and indirectly, insulin action in fat cells, only CIDEA, PDE3B and receptors for testosterone displayed different expression in men with obesity (higher values) compared with women with obesity." (PMID 38491191, 2024). "Pde3b is involved in insulin signalization and is related to obesity and diabetes." (PMID 39484291, 2024). "Obesity-induced changes in serum-cholesterol were blocked in PDE3B−/−mice." (PMID 27321128, 2016). "Reduced ratio of pSmad/Smad in PDE3B−/−WAT suggest that PDE3B regulation of TGF-β/smad signaling may play a role in the effects of smad signaling in the pathogenesis of obesity, inflammation and development of insulin resistance." (PMID 27321128, 2016). "In this study, we identified pLOF variants that protect against obesity (GPR151), asthma (GSDMB, IL33), autoimmune disorders (IFIH1), and coronary artery disease (PDE3B), prioritizing genes and pathways for which pharmacologic attempts to mimic these protective mutations might ameliorate disease." (PMID 29691411, 2018). "Thus, adipocyte PDE3B, and/or cAMP pathways regulated by PDE3B, may provide new targets for the development of anti-obesity drugs designed to produce beneficial effects by inducing the beige phenotype in WAT." (PMID 28084425, 2017). "In this study, we present clear data supporting the function of PDE3B inhibition in raising energy expenditure by promoting WAT browning and highlight the possible therapeutic effects of cilostazol on obesity and obesity-related complications, such as hepatic steatosis." (PMID 36009398, 2022). "However, there were some differences in DCM from obesity—MBD6, CREB5, and PDE3B were down-regulated and the others were up-regulated." (PMID 36547458, 2022). "In adipose tissue of obesity, TNF-α is found to impair the activity of PDE3B." (PMID 30154727, 2018). "Thus, cAMP/PKA-signaling regulated by PDE3B in adipose tissue and potential targeting of caspase-1 activation through NLRP3 inflammasome, may be a new therapeutic target for the development of anti-obesity and anti-inflammatory drugs." (PMID 27321128, 2016).
Insulin resistance (17 papers, 2010 to 2025). Increased resistance towards insulin, that is, diminished effectiveness of insulin in reducing blood glucose levels. "Arsenic exposure can also decrease PDE3b (phosphodiesterase 3b) expression and activity, an enzyme that regulates lipolysis and glucose uptake in adipocytes, resulting in hyperglycemia and insulin resistance." (PMID 37886432, 2023). "In particular, the role of phosphodiesterase 3B on insulin resistance consequent to a long-term niacin treatment has been proposed." (PMID 37535643, 2023). "On the other hand, in a study with mice overexpressing PDE3B, there was an early and striking appearance of hyperglycemia, islet dysfunction, glucose intolerance, insulin resistance, and hepatic steatosis when challenged with HFD." (PMID 36009398, 2022). "Overexpression (2–3 fold) of PDE3B and special diet (HFD) in RIP-PDE3B/2 mouse contributed to hyperglycemia, pancreatic dysfunction of islets, intolerance of glucose, and insulin resistance, which developed suddenly and blunted insulin secretion." (PMID 33153226, 2020). "Pde3b-knockout mice exhibited multiple alterations in regulation of lipolysis, lipogenesis, and insulin secretion, as well as signs of peripheral insulin resistance." (PMID 28430825, 2017). "It has been observed that PDE3A, PDE3B, PDE4B, PDE4D, and PDE8B in rat islets and in INS-1E cells activate multiple signal pathways critical for pancreatic beta cell function, and their abnormalities are associated with insulin resistance." (PMID 35046895, 2021). "PDE3B-overexpressing mice have insulin resistance, islet dysfunction, and glucose intolerance." (PMID 30635550, 2019). "Also inhibition of PDE3B in adipocytes would counteract with the insulin induced antilipolysis, which would increase fatty acid release resulting in insulin resistance." (PMID 23493150, 2012). "The IPGTT revealed that the reduced expression of PDE3B and NLRP3 inflammasome led to substantial protection against HFD-induced insulin resistance." (PMID 27321128, 2016). "Insulin resistance in adipocytes and hepatocytes could further accentuate the negative effects of PDE3 inhibitors in these cells, because insulin utilizes PDE3B to antagonize the effects of catecholamines/cAMP." (PMID 23493150, 2012). "Further, RIP-PDE3B mice overexpressing PDE3B specifically in β-cells show impaired GSIS as well as cAMP-potentiated GSIS, impaired glucose tolerance and increased sensitivity to high-fat induced insulin resistance." (PMID 21152070, 2010).
breast carcinoma (4 papers, 2018 to 2025). "This study focuses on identifying and validating two genes, PDE3B and HBB, that were implicated in breast cancer progression through an integrative analysis of scRNA-seq, TCGA, and an independent patient cohort." (PMID 40462176, 2025). "Our findings provide the first evidence that PDE3B not only correlates with breast cancer proliferation but also serves as a robust prognostic marker." (PMID 40462176, 2025). "To explore the role of PDE3B in breast cancer cell proliferation, we performed Western blot analysis across multiple breast cancer cell lines." (PMID 40462176, 2025). "Adapting a similar strategy to generate subtype-specific breast cancer models—be they 2D cell lines, 3D spheroids, or patient-derived organoids—would provide a powerful platform to dissect the mechanistic roles of PDE3B and HBB in tumor growth, proliferation, and immune crosstalk." (PMID 40462176, 2025). "Furthermore, a scatter plot analysis confirmed a positive correlation between PDE3B protein levels and cell proliferation rates, suggesting that PDE3B expression may promote cellular proliferation in breast cancer cells." (PMID 40462176, 2025). "In this study, we identified and validated PDE3B and HBB as potential prognostic biomarkers in breast cancer through integrative bioinformatic analyses and experimental validation." (PMID 40462176, 2025). "To explore the roles of PDE3B and HBB in breast cancer proliferation, we established overexpression (OE) and knockout (KO) models in MDA-MB-231 cells." (PMID 40462176, 2025). "Experimental validation using MDA-MB-231 cells demonstrated that both PDE3B and HBB significantly promote breast cancer cell proliferation." (PMID 40462176, 2025). "To investigate the relationship between PDE3B and HBB expression and immune infiltration, we utilized EPIC deconvolution to quantify immune cell fractions in TCGA breast cancer samples." (PMID 40462176, 2025). "Our study integrates single-cell RNA-seq, TCGA data analysis, and experimental validation to investigate the roles of PDE3B and HBB in breast cancer proliferation and their potential as prognostic biomarkers." (PMID 40462176, 2025). "The findings not only corroborate previous research on tumor heterogeneity but also provide novel insights into the functional roles of PDE3B and HBB in driving breast cancer progression." (PMID 40462176, 2025). "In summary, our study identifies PDE3B and HBB as key drivers of breast cancer cell proliferation and predictors of poor prognosis." (PMID 40462176, 2025). "This study explores the prognostic and functional roles of PDE3B and HBB in breast cancer, focusing on their contributions to proliferation and immune microenvironment modulation." (PMID 40462176, 2025). "PDE3B and HBB drive breast cancer proliferation and immune modulation, making them promising biomarkers and therapeutic targets." (PMID 40462176, 2025). "By combining bioinformatics analysis and experimental validation, this work highlights PDE3B and HBB as potential prognostic biomarkers and therapeutic targets for breast cancer, providing a deeper understanding of the molecular mechanisms underlying tumor heterogeneity and progression." (PMID 40462176, 2025). "It was proved that metformin can directly affect primary breast cancer in vivo, including the downregulation of phosphodiesterase 3B (PDE3B), a critical regulator of cAMP synthesis, which combined with AMPK activation, can be considered as adjuvant breast cancer therapy." (PMID 35267644, 2022). "In addition, PDE3B-mediated cAMP hydrolysis limits the antiangiogenic potential of PKA in endothelial cells, suggesting PDE3B regulates angiogenesis and inhibits the occurrence and metastasis of breast cancer by controlling the invasion ability of endothelial cells." (PMID 37024893, 2023). "This analysis identified two genes, PDE3B and HBB, with nonzero coefficients, indicating their potential roles in breast cancer prognosis." (PMID 40462176, 2025).
diabetes (4 papers, 2017 to 2024). "It is thus clear that DG might inhibit STZ-treated pancreatic β-cell apoptosis and reduce dysfunction via downregulating PDE3B, which provided a more reliable theoretical basis for the treatment of diabetes mellitus with DG." (PMID 35030973, 2022).
chronic lymphocytic leukemia (3 papers, 2013 to 2025). "Additionally, Moon and colleagues (2002) found that inhibiting PDE3-B and PDE4 increased apoptosis in certain patients with chronic lymphocytic leukemia." (PMID 40535773, 2025).
colon cancer (3 papers, 2013 to 2024). "High level of PDE3B was observed in colon cancer tissues and associated with cell proliferation." (PMID 38774995, 2024). "Based on our results, we suggest that elucidating the molecular mechanisms by which cPA induces cAMP production by inhibiting PDE3B in colon cancer cells can provide valuable insights that help explain how cancer cell growth is regulated." (PMID 24282571, 2013). "Our results suggest that PDE3B expression and intracellular cAMP levels are correlated with the proliferation of colon cancer cells." (PMID 24282571, 2013). "PDE3B expression and intracellular cAMP levels are correlated with the proliferation potential of colon cancer cells." (PMID 24282571, 2013). "PDE3B mRNA and protein were expressed at high levels in HT-29 cells, and we observed that PDE3B expression levels correlated with colon cancer cell proliferation." (PMID 24282571, 2013). "To evaluate the function of PDE3 in human colon cancer cells, we used 4 colon cancer cell lines, HT-29, LOVO, DLD-1, and Caco-2, and examined the expression of PDE3B protein in these cell lines." (PMID 24282571, 2013). "In the context of colon cancer, the PDE3-specific inhibitor cilostazol, which has been used previously to treat patients with thrombosis, was used to assess the effects of PDE3B inhibition on cellular growth." (PMID 24282571, 2013).
fatty liver (3 papers, 2009 to 2025). "Copper attenuates liver steatosis in two different ways: first, by inhibition of PDE3B, an enzyme of lipolysis, and second, by lipogenesis enhancement through the activation of the Nrf2-PPARγ pathway." (PMID 39781288, 2025). "Dysregulation of PDE3B could have a role in the development of fatty liver, a condition highly relevant in the context of type 2 diabetes." (PMID 19262749, 2009).
Glucose intolerance (3 papers, 2009 to 2022). Glucose intolerance (GI) can be defined as dysglycemia that comprises both prediabetes and diabetes. "For example, mice that specifically overexpress PDE3B in pancreatic β-cells demonstrate glucose intolerance and impaired insulin response to glucose and glucagon-like peptide-1 (GLP-1)." (PMID 19262749, 2009). "Hence, on one hand PDE3B KO mice are lean and have improved insulin secretion but they also exhibit glucose intolerance, insulin resistance and increased lipolysis." (PMID 19262749, 2009).
atherosclerosis (2 papers, 2016 to 2020). A disease characterized by the build-up of fatty material and calcium deposition in the arterial wall resulting in partial or complete occlusion of the arterial lumen. "A loop of has-circ-0028198/has-circ-0092317/XIST/miR-543/aspartate beta-hydroxylase or has-circ-0028198/has-circ-0092317/XIST/miR-543/phosphodiesterase 3B has been implicated in oxidized, low-density, lipoprotein-stimulated foam cells in atherosclerosis." (PMID 32293498, 2020). "We were interested to know if reduced expression of PDE3B will help in moderation of atherosclerosis in apoE−/−and LDL-R−/−mice." (PMID 27321128, 2016).
autoimmune disease (2 papers, 2018 to 2019). A disorder resulting from loss of function or tissue destruction of an organ or multiple organs, arising from humoral or cellular immune responses of the individual to their own tissue constituents. "Disruption of PDE3B activity through pharmacological inhibition or genetic ablation restores TregΔ142 Treg–suppressive function and prevents lethal autoimmune disease." (PMID 30741720, 2019). "Pharmacological inhibition and genetic ablation of PDE3B prevented autoimmune disease and reversed the impaired suppressive function of Tregs in TregΔ142 animals." (PMID 30741720, 2019). "Suppression of miR-142 expression in CD4+ T cells from patients suffering from autoimmune diseases such as SLE predicts that PDE3B expression and activity may be enhanced in these cells and that this may underlie disease etiology." (PMID 30741720, 2019). "In light of our findings, there is now a precedent for further investigation to establish whether modulation of PDE3B activity in Tregs may help to reestablish mechanisms of tolerance in patients suffering from autoimmune disease." (PMID 30741720, 2019).
colorectal cancer (2 papers, 2019 to 2023). A primary or metastatic malignant neoplasm that affects the colon or rectum. "With respect to cancers, overexpression of PDE3B and lower cyclic AMP levels have been observed in colorectal cancers and gastrointestinal stromal tumor." (PMID 36348017, 2023). "Furthermore, in colorectal cancer, curcumin can modulate gene expression of HSPA5, SEC61B, G6PD, HMOX1, and PDE3B, affecting essential pathways like DNA replication or the cell cycle." (PMID 31744117, 2019).
dyslipidemia (2 papers, 2018 to 2020). "The association of PDE3B pLOFs with improved body fat distribution, reduced risk of hypercholesterolemia and reduced risk of coronary artery disease suggests that selective inhibition of PDE3B may be useful for multiple features of metabolic syndrome." (PMID 29691411, 2018).
periodontitis (2 papers, 2020 to 2022). An acute or chronic inflammatory process that affects the tissues that surround and support the teeth. "In subjects with well-controlled T2DM plus DL plus periodontitis versus HS, there were 3 DEG genes (BPTF, PDE3B, and FN1)." (PMID 36233348, 2022).